ZNF419 (zinc finger protein 419)
Description:
May be involved in transcriptional regulation.
Synonyms: ZNF419A; ZAPHIR
Tractability: PROTAC: UniProt records ubiquitination sites on it; ubiquitination databases record sites on it.
Gene: Protein-coding gene on chromosome 19 (57,487,711 to 57,496,098, forward strand). Ensembl gene ENSG00000105136.
Subcellular location: Nucleus
Subcellular location (Human Protein Atlas): Nucleoplasm; Nucleoli fibrillar center
Pathways (Reactome):
Gene expression (Transcription): Generic Transcription Pathway
Gene Ontology:
Molecular function: protein binding; DNA-binding transcription factor activity, RNA polymerase II-specific; RNA polymerase II cis-regulatory region sequence-specific DNA binding
Biological process: regulation of transcription by RNA polymerase II; regulation of DNA-templated transcription
Cellular component: nucleus
Genetic constraint (gnomAD): Loss-of-function variants: 8 observed, 15.59 expected, observed/expected ratio (o/e) 0.51, 90% interval 0.3 to 0.93. The upper end of that interval is the gene's LOEUF score, 0.93, which puts it in group 3 of 6, group 1 being the genes least tolerant of losing a copy. Missense variants: 595 observed, 612.92 expected, observed/expected ratio (o/e) 0.97, 90% interval 0.91 to 1.04. Synonymous variants: 211 observed, 209.05 expected, observed/expected ratio (o/e) 1.01, 90% interval 0.9 to 1.13.
Homologues: Orthologues: macaque ZNF419 (92% identical), rat Zfy1 (20% identical), mouse Zfy1 (20% identical), tropical clawed frog zfx (19% identical), mouse Zfy2 (19% identical), zebrafish zfx (19% identical). Paralogues in human: ZNF773 (79% identical), ZNF304 (45% identical), ZNF256 (45% identical), ZNF792 (43% identical), ZNF551 (42% identical), ZNF549 (42% identical), ZNF587B (41% identical), ZNF548 (41% identical), ZNF418 (39% identical), ZNF772 (39% identical), ZIK1 (37% identical), ZNF570 (37% identical), and 26 more.
Diseases named in the same sentence as ZNF419 in open-access papers:
ZNF419 is named in the same sentence as 13 diseases in open-access papers, as found by Europe PMC text mining. Sharing a sentence is not in itself a finding about the gene and the disease. The quoted sentences say what the papers report.
renal cell carcinoma (4 papers, 2011 to 2022). "As a ferroptosis-related gene, the polymorphism of zinc finger protein 419 (ZNF419) at the splice donor site may generate renal cell carcinoma-associated novel minor histocompatibility antigen ZAPHIR." (PMID 36578929, 2022). "Polymorphism of ZNF419 at the splice donor site may generate renal cell carcinoma-associated novel minor histocompatibility antigen ZAPHIR." (PMID 36578929, 2022). "As a transcriptional regulator, ZNF419 polymorphism at the splice donor site might result in novel minor histocompatibility antigen ZAPHIR related to renal cell carcinoma." (PMID 34291083, 2021). "A polymorphism at a splice donor site in ZNF419 produces ZAPHIR, an alternatively spliced polymorphic histocompatibility antigen in renal cell carcinoma." (PMID 29299175, 2017).
bladder cancer (1 paper, 2021). "The TP63, CAPG, SCD, and ZNF419 were found to be significantly upregulated in the bladder cancer tissue samples." (PMID 34386423, 2021).
epithelial ovarian cancer (1 paper, 2022). "Consistent with our results, previous studies revealed the diagnostic and prognostic value of ZNF419 based on its role in immune regulation in epithelial ovarian cancer, esophageal cancer, and renal cancer." (PMID 36578929, 2022). "They found significantly differential expression of ZNF419 between ovarian cancer tissues and normal control tissues, while we did not, which was possibly attributed to the difference in tumor samples." (PMID 36578929, 2022).
esophageal cancer (1 paper, 2022). A primary or metastatic malignant neoplasm involving the esophagus. "The differential expression of ZNF419 between tumor and normal samples was analyzed and we found that ZNF419 was significantly expressed in most cancers, including PRAD, stomach and esophageal carcinoma (STES), KIRC, LUSC, LIHC, and BLCA." (PMID 36578929, 2022).
Fanconi anemia complementation group D2 (1 paper, 2022). Fanconi anemia caused by mutations of the FANCD2 gene. "Mechanically, we revealed the potential role of ZNF419 in pan-cancer from the perspective of ferroptosis, in which Fanconi anemia complementation group D2 (FANCD2) may serve as a bridge gene along with ZNF419 and ferroptosis." (PMID 36578929, 2022).
renal carcinoma (1 paper, 2022). A carcinoma arising from the epithelium of the renal parenchyma or the renal pelvis. "We hypothesize that this opposite situation may be ascribed to epigenetic regulation, since previous studies have confirmed the alternative splicing polymorphisms of ZNF419 and its related underlying effect in renal cancer." (PMID 36578929, 2022).
cancer (6 papers, 2021 to 2025). A tumor composed of atypical neoplastic, often pleomorphic cells that invade other tissues. "In our results, high expression of ZNF419 was associated with a good prognosis in some cancers, while in others, low expression of ZNF419 was correlated with a poor prognosis." (PMID 36578929, 2022). "Additionally, our findings indicated the potential mechanisms of ZNF419 expression in tumor heterogeneity, signaling pathways, immunity, and mutations from a pan-cancer perspective." (PMID 36578929, 2022). "In addition, to explore the association between ZNF419 expression level and prognosis, we conducted a pan-cancer survival analysis with OS, DSS, and PFI." (PMID 36578929, 2022). "Our study showed that ZNF419 expression was associated with TMB in 14 cancer species." (PMID 36578929, 2022). "Transcription factor activity analysis revealed a significant upregulation of ZNF419 in CAFs, a marker previously identified in studies as indicative of immune microenvironment alterations and an adverse prognosis in cancer." (PMID 39950116, 2025). "Previous studies have identified ZNF419 as a marker for immune microenvironment alterations and adverse prognosis in cancer and as a promising candidate therapeutic target." (PMID 41584584, 2025). "To illustrate the possible links between ZNF419 expression and immune status in tumors, we conducted an analysis of immune-related genes and immune infiltration conditions in the TME, to explore the role of ZNF419 across cancers from an immune perspective." (PMID 36578929, 2022). "Our study shows that ZNF419 can be used as an independent prognostic factor for a variety of cancers and that ZNF419 also plays an important role in tumor immunity." (PMID 36578929, 2022). "This study aimed to visualize the prognostic landscape of ZNF419 at pan-cancer level and explore the relationship between ZNF419 expression and the tumor immune microenvironment." (PMID 36578929, 2022). "There has yet to be any pan-cancer research into the relationship between ZNF419 expression and multiple cancers." (PMID 36578929, 2022). "Our results demonstrated that in 11 cancers, including PRAD, LUSC, and BLCA, ZNF419 expression was associated with MSI, and that ZNF419 expression was negatively related to NEO in another four cancers." (PMID 36578929, 2022). "It is meaningful that increasing evidence has shown the underlying roles of zinc finger proteins in cancer progression, indicating the potential utility of ZNF419 in cancer research and treatment." (PMID 36578929, 2022). "For each cancer, we divided them into two groups according to the expression level of ZNF419, to explore the possible mechanisms and pathways of ZNF419 related to tumorigenesis and cancer progression through their associated mutated genes." (PMID 36578929, 2022). "First, bioinformatic analyses did provide insights into the significance of ZNF419 across cancers in terms of cancer immunity, clinical prognosis, and other aspects, but it is still essential to conduct biological validation experiments in vitro and in vivo." (PMID 36578929, 2022). "In conclusion, the results of this study clarified the close correlations of ZNF419 expression with diverse human cancer types and its related prognostic value." (PMID 36578929, 2022). "According to our study, ZNF419 is not only a marker for tumor immune microenvironment changes and poor prognosis, but it is also a promising candidate therapeutic target for cancers." (PMID 36578929, 2022). "Our results demonstrated that the expression level of ZNF419 was significantly related to TMB in 14 cancer species, with 5 being positively related, such as GBM and LGG, and 9 being negatively related, such as KIRC and STES." (PMID 36578929, 2022). "To determine the role of ZNF419 in cancer, we evaluated the mRNA expression level of ZNF419 in tumor tissues and adjacent normal tissues." (PMID 36578929, 2022).
cancer (continued). "In addition, these findings also clearly demonstrate that ZNF419 can be utilized as a biomarker to determine the prognosis of various cancers." (PMID 36578929, 2022). "Hence, we used the oncological data for ZNF419 from The Cancer Genome Atlas (TCGA) to determine the prognostic landscape of ZNF419 at the pan-cancer levels." (PMID 36578929, 2022). "However, ZNF419 seemed to be a protective factor in BLCA, KIRC, PRAD and some other cancers because low ZNF419 expression was related to a good prognosis (analyzed by OS, DSS, and PFI)." (PMID 36578929, 2022). "ZNF419 might serve as a potential prognostic and immunological pan-cancer biomarker, especially for KIRC, LIHC, LUSC, PRAD, and BLCA." (PMID 36578929, 2022). "In contrast, although LUSC, BLCA, KIRC and LIHC have been reported to show an inflamed TME and react well to immunotherapy, the high expression level of ZNF419 still weakened the immune infiltration status in the TME of those cancers and ultimately led to poor prognnosis." (PMID 36578929, 2022). "Nonetheless, previous research on ZNF419 in tumors has been limited to a few cancer types." (PMID 36578929, 2022). "The different expression levels of ZNF419 in diverse cancers may result in different prognoses, which requires further study." (PMID 36578929, 2022). "The enriched pathways in KIRC and LIHC were much more than other four cancers, which may indicate more complex mechanisms of ZNF419 in these two cancers." (PMID 36578929, 2022). "Our study also demonstrated that ZNF419 expression was correlated with MSI in 11 cancer types." (PMID 36578929, 2022). "Our results showed that the expression of ZNF419 was significantly high among 12 cancers." (PMID 36578929, 2022). "For instance, ZNF830 promotes homologous-recombination repair and mediates cancer chemoresistance; ZNF281 acts as a potential diagnostic marker for oral squamous cell carcinoma; and ZNF419 might serve as a potential prognostic and immunological pan-cancer biomarker." (PMID 40599863, 2025). "Importantly, our results showed that ZNF419 expression played a vital role in cancer immunity." (PMID 36578929, 2022). "However, there have not yet been enough systematic studies on ZNF419 across cancers, with an underlying and poorly illustrated mechanism in the context of ferroptosis." (PMID 36578929, 2022). "Therefore, the expression of the ferroptosis-related gene ZNF419 may account for another novel point in cancer research as well as cancer therapy." (PMID 36578929, 2022). "The immune and stromal scores, on the other hand, revealed that ZNF419 expression was negatively correlated with the immune score, stromal score, and ESTIMATE score in most cancer types." (PMID 36578929, 2022). "We also observed significant correlations between ZNF419 expression and LOH in various cancers, the majority of which were positive." (PMID 36578929, 2022). "Hence, ZNF419 may regulate ferroptosis through FANCD2 at the pan-cancer level." (PMID 36578929, 2022). "The results showed that ALOX12, ANGPTL7, DRD4, and MAPK9 remarkably decreased within ESCC samples relative to non-carcinoma samples, whereas SLC38A1 and ZNF419 were highly expressed." (PMID 34291083, 2021). "This also suggested that the role of ZNF419 is not exactly the same in different types of cancers, so the therapeutic emphasis is supposed to vary at different cancer types and different cancer stages." (PMID 36578929, 2022). "We also suggested the prognostic value of ZNF419 by analyzing OS, DSS and PFI in different cancers." (PMID 36578929, 2022). "This may suggest that the level of ZNF419 expression affects tumor heterogeneity at genetic or epigenetic level and changes the TMB of cancers, thereby affecting the patient’s response to ICB therapy." (PMID 36578929, 2022). "In terms of MATH, the results showed a positive correlation with the expression of ZNF419 mRNA in 4 types of cancers and a negative correlation in 3 types of cancers." (PMID 36578929, 2022).
cancer (continued). "We found the interaction between ZNF419 and FANCD2 might involve in ferroptosis in pan-cancer level." (PMID 36578929, 2022). "It is worth mentioning that the expression of ZNF419 was associated with a variety of pathways in KIRC and LIHC, which may reveal that ferroptosis is not the only mechanism that ZNF419 is involved in the occurrence and development of pan-cancer." (PMID 36578929, 2022). "The correlations between ZNF419 expression and MATH in 7 cancer types support our hypothesis." (PMID 36578929, 2022). "The significant upregulation of ZNF419 in multiple cancers and the negative correlations between the expression of ZNF419 and different cancer species may suggest that ZNF419 can be regarded as an independent prognostic predictive factor for multiple cancers." (PMID 36578929, 2022). "According to the ESTIMATE algorithm, significant correlations between ZNF419 expression and the content of both immune and stromal cells in the TME were identified in more than 20 cancer types, and most of them were negative, where PRAD, KIRA, LUSC, LIHC, and BLCA were representative cancer types." (PMID 36578929, 2022).
tumor (3 papers, 2013 to 2022). "Not only did ZNF419 employ mutated genes to participate in tumorigenesis and tumor progression, but epigenetic regulation also played an indispensable role." (PMID 36578929, 2022). "ZNF419 was differentially expressed between tumor and normal samples and was associated with overall survival, disease-specific survival and progression-free interval for STES, KIRC, LIHC, LUSC, PRAD, and BLCA." (PMID 36578929, 2022). "We further assessed the relationship between ZNF419 expression and tumor heterogeneity and stemness." (PMID 36578929, 2022). "To determine the exact alterations in tumor-infiltrating immune cells in the TME under the influence of ZNF419 expression, we assessed the infiltration scores of several different cell types in the TME with the assistance of the TIMER and EPIC methods." (PMID 36578929, 2022). "The relationships between ZNF419 expression and tumor immunity were investigated through the TIMER and ESTIMATE methods." (PMID 36578929, 2022). "In summary, our study revealed the unique role of the ferroptotic gene ZNF419 in tumor immunity." (PMID 36578929, 2022). "These significant correlations may indicate the potential relationship of ZNF419 expression with mutation and mutation derived heterogeneity due to the characteristic of MATH in reflecting the frequency of all mutant alleles in the tumor by clustering." (PMID 36578929, 2022).
ZNF419 also shares sentences with these, for which no sentence is quoted: brain tumor (1 paper); cystadenoma (1); ovarian cancer (1); prostate adenocarcinoma (1); stomach (1).